INS (insulin)
Diseases named in the same sentence as INS in open-access papers (continued):
Sharing a sentence is not in itself a finding about the gene and the disease.
vitamin B12 deficiency (3 papers, 2014 to 2025). A disease characterized by low serum levels of vitamin B12, either inherited or acquired. "The patients treated with metformin plus sulfonylurea (S+M group) showed a significantly higher prevalence of vitamin B12 deficiency compared with those treated with metformin plus insulin (I+M group) for the same time period." (PMID 25299054, 2014). "After adjusting for confounding factors, the sulfonylurea combination was significantly associated with metformin-related vitamin B12 deficiency compared with the insulin combination during the same time period." (PMID 25299054, 2014). "As the first-line medication for T2DM, metformin exerts its efficacy through insulin sensitivity enhancement, though prolonged administration may induce gastrointestinal complications (e.g., diarrhea) and vitamin B12 deficiency risks." (PMID 40540468, 2025). "Thus, we focused on the effect of combinations of metformin with either sulfonylurea or insulin, which are frequently used hypoglycemic agents, on vitamin B12 deficiency during the same time period." (PMID 25299054, 2014).
21-hydroxylase deficiency (2 papers, 2024 to 2025). "Fasting blood was obtained for visfatin, leptin, adiponectin, glucose, insulin, CRP, lipid panel, total cholesterol (TC), triglycerides (TG) and HbA1c, as well as standard laboratory tests to assess adrenal control, from children with CAH due to 21-hydroxylase deficiency." (PMID 39175574, 2024).
acute aortic dissection (2 papers, 2023 to 2025). "This study provides novel evidence that elevated insulin resistance indices, particularly the TyG index, independently predict MACCEs in patients with acute aortic dissection." (PMID 41584289, 2025). "A previous experimental study indicated that short-term coffee consumption could impair glucose tolerance and reduce insulin sensitivity due to the A1 attenuating aortic dissection affected by the caffeine-blocking; however, this effect will not last long." (PMID 36860390, 2023).
acute intermittent porphyria (2 papers, 2021 to 2022). Acute intermittent porphyria is the most frequent and the most severe form of the acute hepatic porphyrias. "In the inherited metabolic disorder acute intermittent porphyria (AIP), high sugar intake prevents porphyric attacks due to the glucose effect and the following high insulin levels that may lower AIP disease activity." (PMID 36013449, 2022).
acute promyelocytic leukemia (2 papers, 2012 to 2018). An aggressive form of acute myeloid leukemia (AML), characterized by arrest of leukocyte differentiation at the promyelocyte stage, due to a specific chromosomal translocation t(15;17) in myeloid cells. "S-glutathionylation of UCP2, which is more ubiquitously expressed, was found to regulate insulin release by altering mitochondrial ROS release in pancreatic β-cells and sensitize drug resistant promyelocytic leukemia cells to chemotherapy." (PMID 29444156, 2018). "HL-60 cells have been reported to have an absolute requirement of transferrin and insulin for cell proliferation, and have been widely used as a model system for the study of myeloid differentiation, hematopoiesis, and acute promyelocytic leukemia." (PMID 23194296, 2012).
adrenal tumour (2 papers, 2024). "Appreciable insulin occurred in transplants of a hamster and a mouse adrenal tumour." (PMID 5451575).
alexithymia (2 papers, 2013 to 2020). An agnosia that is a deficiency in understanding, processing, or describing emotions. "Individuals with alexithymia may be unaware of their physical symptoms when they need more insulin and, as a result, they overlook their abilities of self-care." (PMID 32252831, 2020).
allergic contact dermatitis (2 papers, 2023 to 2025). An inflammatory skin condition caused by an immune response to direct contact between the skin and an allergen. "Skin reactions related to medical device use: Repeated insulin injections, continuous glucose monitoring sensors, and insulin pumps can cause lipohypertrophy, lipoatrophy, or allergic contact dermatitis due to adhesives or preservatives." (PMID 41227114, 2025).
angioedema (2 papers, 2014 to 2024). Swelling involving the deep dermis, subcutaneous, or submucosal tissues, representing localized edema. "The one patient who was hypotensive/had angioedema was on insulin detemir and digoxin at home (P < 0.001) and had a pacemaker (P = 0.048)." (PMID 39211672, 2024).
aniridia (2 papers, 2021 to 2026). Aniridia is a congenital ocular malformation characterized by the complete or partial absence of the iris. "Recently in families with congenital aniridia it has been suggested that PAX6 mutations and glucose metabolism may be associated; with case-control suggesting that the production of proinsulin to insulin may include participation from the PAX6 gene." (PMID 34970513, 2021).
Arterial Disease (2 papers, 2020 to 2022). "Fourth, due to the low risk of thromboembolic events in the included patients, our results might not be apply to high-risk patients, such as those with DM who require insulin therapy, having lower extremity arterial disease, or experienced previous stent thrombosis." (PMID 33326442, 2020).
asthenia (2 papers, 2021 to 2024). Clinical sign or symptom manifested as debility, or lack or loss of strength and energy. "On the other hand, physical inactivity, unbalanced nutrition and unhealthy lifestyles continue after cancer treatment, and may also be responsible for asthenia and FFM reduction, which in turn induce a decrease in insulin-stimulated glucose uptake." (PMID 33802940, 2021).
atrial septal defect (2 papers, 2012 to 2014). Interauricular communication is a congenital malformation characterized by a communication between the atrial chambers of the heart. "While only minor differences were observed among the significant associations found, this was the case for, e.g. insulin and severe ear malformation, atrial septal defect, and axial skeletal malformations; and for acetaminophen and multiple joint contractures." (PMID 23056376, 2012). "Severe ear malformation, ventricular septal defect, atrial septal defect, and axial skeletal malformations were significantly associated with insulin by SICK, OECA and HEALTHY designs in our work." (PMID 23056376, 2012). "Atrial septal defect (Q21.1), axial skeletal malformations (Q67.5; Q76.0–Q76.8), severe ear malformation (Q16.0 and Q17.2), and ventricular septal defect (Q21.0) showed a strong association with insulin exposure using SICK and OECA approaches." (PMID 23056376, 2012).
autoimmune haemolytic anaemia (2 papers, 2014 to 2023). "Three months before admission, she was diagnosed with autoimmune hemolytic anemia (AIHA) and was started on 70mg oral prednisolone per day, which exacerbated her diabetes, necessitating intensive insulin therapy." (PMID 24524438, 2014).
bacterial meningitis (2 papers, 2009 to 2022). Inflammation of the membranes surrounding the brain and spinal cord due to a bacterial infection. "Additionally, the cumulative concentration of sugar in the blood due to insulin resistance or less production of insulin may provide a conductive environment for fungal or bacterial growth in the body, thus giving more room for the development of bacterial infections such as bacterial meningitis." (PMID 36570413, 2022). "The question arises whether intensive insulin therapy is feasible, safe and effective when implemented outside of the ICU, where most patients with acute bacterial meningitis are managed." (PMID 19426501, 2009).
benign intracranial hypertension (2 papers, 2021 to 2025). "Although GH therapy has a good safety profile in girls with TS, close monitoring of IGF1 levels, abnormal glucose tolerance, reduced insulin sensitivity, benign intracranial hypertension, scoliosis and other skeletal changes at intervals of 3–6 months-is recommended." (PMID 34893062, 2021).
bladder infection (2 papers, 2022 to 2025). "In addition, insulin reduces the risk factor of blood sugar, thereby reducing the susceptibility of diabetic patients to bladder infection of UPEC, K.pneumoniae, E.faecalis, GBS, S.aureus, and Candida.." (PMID 36081496, 2022). "Among hormones, insulin has the ability to promote the secretion of RNase 7, RNase4, and LCN2, which are proven to be against bladder infection caused by a variety of uropathogens." (PMID 36081496, 2022). "Except for insulin, estrogen also changes the bacterial burden in bladder infection." (PMID 36081496, 2022).
brain inflammation (2 papers, 2023 to 2024). "Additional end-points included whole body and hepatic insulin sensitivity, MRI-measured brain inflammation and insulin resistance, intestinal permeability (via lactulose-mannitol test and plasma zonulin levels), and gut microbiome composition." (PMID 39593091, 2024).
bronchitis (2 papers, 2022). An acute or chronic inflammatory process affecting the bronchi. "At the same time, none of the studies evaluated the level of C-peptide and insulin in individuals with combined pathology of AO and bronchitis." (PMID 36291711, 2022).
cancer resistance (2 papers, 2021 to 2025). "These mice also show improved aging phenotypes, with extended lifespan in females and enhanced insulin sensitivity and cancer resistance in males." (PMID 41350448, 2025). "Importantly, females exhibited significant mean, median, and maximal lifespan extension while improved insulin sensitivity, cancer resistance, and a trend to extend median lifespan was seen in males." (PMID 34811874, 2021).
candidiasis (2 papers, 2017 to 2022). Infection with the organism Candida. "Hence, salivary glucose level decreased after beginning insulin treatment in both children and adolescents, while infections (e.g candidiasis in those with dentures or HIV) and inflammation of salivary glands could increase the glucose level in saliva." (PMID 28127542, 2017).
cardiac interstitial fibrosis (2 papers, 2016 to 2021). "However, cardiac interstitial fibrosis was markedly increased in STZ control hearts, which, consistent with the diastolic function data, was attenuated by exendin-4, but not insulin." (PMID 26597728, 2016).
catecholaminergic polymorphic ventricular tachycardia (2 papers, 2016 to 2017). Catecholaminergic polymorphic ventricular tachycardia (CPVT) is a severe genetic arrhythmogenic disorder characterized by adrenergically induced ventricular tachycardia (VT) manifesting as syncope and sudden death. "Interestingly, catecholaminergic polymorphic ventricular tachycardia (CPVT) is caused by RyR2 mutation, and patients suffering from this condition are also prone to impaired glucose homeostasis and insulin secretion." (PMID 27642609, 2016).
cerebral amyloid angiopathy (2 papers, 2017 to 2023). "We hypothesized that CST3 plays a crucial role in the development of T2D-induced AD pathology through the regulation of cerebral amyloid angiopathy and insulin signaling in a dose dependent manner." (PMID 37342358, 2023).
chondrosarcoma (2 papers, 2002 to 2019). A malignant cartilaginous matrix-producing mesenchymal neoplasm arising from the bone and soft tissue. "Accordingly, cell culture experiments based on rat- or human-derived (OUMS-27) chondrosarcoma cells with HI (10 μg/mL) or lower levels (1 μg/mL insulin) demonstrated the dependence of chondrosarcoma cell growth, PG and collagen synthesis on insulin." (PMID 30759730, 2019).
Chronic colitis (2 papers, 2023 to 2024). A chronic inflammatory disease of the large intestine (colon, cecum and rectum). "Based on it, we examined the function of rectal insulin instillation in a dextran sodium sulfate (DSS) induced chronic colitis." (PMID 38243324, 2024). "Rectal insulin instillation promoted EZH2 expression and EZH2 inhibition alleviated chronic colitis." (PMID 38243324, 2024).
chronic fatigue syndrome (2 papers, 2015 to 2024). "Interestingly, glucose uptake in response to insulin was normal in the chronic fatigue syndrome cultures, pointing to a specific exercise related defect." (PMID 25836975, 2015).
colon polyps (2 papers, 2023 to 2025). "Excesses of GH and IGF-I lead to remodelling of tissues and organs, including the heart and vessels; increases in lipolysis and insulin resistance; disruption of bone turnover; and predisposition of the patient to thyroid enlargement and colon polyps." (PMID 37189829, 2023). "In an Italian cohort, colon polyps were found to be positively associated with GH, IGF-1, fasting glucose, and insulin levels." (PMID 40167828, 2025).
contact dermatitis (2 papers, 2023 to 2024). An inflammatory skin condition caused by direct contact between the skin and either an irritating substance or an allergen. "Nonetheless, contact dermatitis elicited by the use of insulin pumps and/or glucose sensors can be either allergic or irritant." (PMID 37445875, 2023). "Finally, not every patient using insulin pumps and/or glucose sensors eventually elicits contact dermatitis." (PMID 37445875, 2023).
coronary artery stenosis (2 papers, 2014 to 2021). "In conclusion, the rs1324551 SNP in the promoter region of the ACTA2 gene was identified to be independently correlated with the degree of coronary artery stenosis in patients with T2DM and plasma insulin may inhibit coronary artery stenosis during the pathogenic process." (PMID 24669260, 2014). "One patient randomized to insulin discontinued because of coronary artery stenosis during the extension phase." (PMID 34275099, 2021). "This indicates that plasma insulin may have a protective role in coronary artery stenosis in patients with T2DM." (PMID 24669260, 2014). "At present, the role of insulin in coronary artery stenosis remains controversial." (PMID 24669260, 2014). "In the present study, the correlation between SNPs in the promoter region of the ACTA2 gene and coronary artery stenosis in patients with T2DM was investigated, and the interaction of SNPs with plasma insulin was further analyzed." (PMID 24669260, 2014).
Crush Syndrome (2 papers, 2016 to 2019). Severe systemic manifestation of trauma and ischemia involving soft tissues, principally skeletal muscle, due to prolonged severe crushing. "Treatment with Ani significantly enhanced insulin sensitivity in mice with crush syndrome, reflected by reduced serum insulin (P < 0.05), glucose (P < 0.01), and HOMA-IR (P < 0.05), and elevated QUICKI index (P < 0.05)." (PMID 27065867, 2016). "Ani reduced mortality and serum potassium and enhanced insulin sensitivity shortly after decompression in animals with crush syndrome, and PNU282987 exerted similar effects." (PMID 27065867, 2016). "The major findings of the present study include: (i) activation of α7nAChR with Ani decreases on-site mortality in crush syndrome; (ii) such effect of activating α7nAChR is partially due to decline of serum potassium; (iii) Ani decreases serum potassium through insulin signaling-Na/K-ATPase pathway." (PMID 27065867, 2016). "This study demonstrates that activation of α7nAChR could decrease on-site mortality in crush syndrome based on the decline of serum potassium through insulin signaling-Na/K-ATPase pathway." (PMID 27065867, 2016). "Serum insulin and glucose levels and HOMA-IR were substantially increased, and QUICKI index was markedly decreased in rats with crush syndrome compared with normal rats." (PMID 27065867, 2016). "Involvement of insulin sensitivity and Na/K-ATPase in the reduction of on-site mortality in crush syndrome by activation of α7nAChR was not proved by corresponding inhibitors in vivo, considering the possibility that the mortality may be increased by disorders in serum glucose and energy supply." (PMID 27065867, 2016).
dermatomyositis (2 papers, 2024 to 2026). Dermatomyositis (DM) is a type of idiopathic inflammatory myopathy characterized by evocative skin lesions and symmetrical proximal muscle weakness. "Network toxicology analysis suggested that BPA may influence the progression of dermatomyositis by regulating key factors such as AKT1, BCL2, MMP9, ESR1, and INS, thereby affecting apoptosis, immune-inflammatory responses, pathways in cancer, and the PI3K-Akt signaling pathway." (PMID 41911226, 2026).
diarrheal disease (2 papers, 2016 to 2023). The condition of having at least three loose or liquid bowel movements each day. "Furthermore, altering the activities of angiotensin-converting enzymes (ACEs) and endothelin-converting enzymes or insulin-degrading enzyme would have potential to affect blood pressure or insulin levels, which would not be desirable in diarrheal disease states." (PMID 26907621, 2016).
ductal adenocarcinoma (2 papers, 2014 to 2023). "Our data suggest that during ductal adenocarcinoma development the vitamin D system in the pancreas becomes deregulated on two levels: in the islets CYP24A1 expression decreases weakening the negative feedback regulation of the vitamin D-dependent insulin synthesis/secretion." (PMID 25090635, 2014). "Further, our data suggest that during ductal adenocarcinoma development the vitamin D system in the pancreas becomes deregulated on two levels: In the islets CYP24A1 expression decreases weakening the negative feedback regulation of the vitamin D-dependent insulin synthesis and secretion." (PMID 25090635, 2014).
Dyskinesia (2 papers, 2023 to 2025). A movement disorder which consists of effects including diminished voluntary movements and the presence of involuntary movements. "Their actions on brain insulin signaling, neuroinflammation, oxidative stress, and mitochondrial function likely contribute to improvements in motor and non-motor symptoms, including cognition, mood, and apathy, while maintaining a neutral effect on dyskinesias." (PMID 41003884, 2025).
Dystonia (2 papers, 2008 to 2016). An abnormally increased muscular tone that causes fixed abnormal postures. "We treated the patient’s hyperglycaemia with intravenous insulin and the dystonia disappeared within 5 days." (PMID 27549630, 2016). "We treated the patient with continuous intravenous regular insulin infusion and medication with haloperidol, and dystonia completely disappeared within 3 days." (PMID 19017374, 2008). "We treated the patient with a continuous intravenous regular insulin infusion and medication with haloperidol, and dystonia completely disappeared within 3 days." (PMID 19017374, 2008).
dystrophin deficiency (2 papers, 2018 to 2023). "In addition to the mechanical fragility of the sarcolemma, dystrophin deficiency is characterized by metabolic dysregulation, manifesting as reduced glycolytic enzymes, mitochondrial structural and functional abnormalities, and altered glucose uptake and response to insulin." (PMID 29508262, 2018).
endometrial polyp (2 papers, 2023 to 2024). A benign nodular lesion protruding above the surface of the endometrium. "Therefore, the regulation of insulin signaling and glucose metabolism may be a promising target for the prevention and treatment of endometrial polyps and related reproductive disorders." (PMID 38909214, 2024).
Ewing sarcoma (2 papers, 2013 to 2020). A small round cell tumor that lacks morphologic, immunohistochemical, and electron microscopic evidence of neuroectodermal differentiation. "Our preclinical data supports that insulin clearly stimulates cell growth and blocks the apoptosis (Figure A1) of Ewing sarcoma cells in vitro." (PMID 33260481, 2020). "This is supported by our data (Figure A2), which showed that insulin reverts the inhibitory effect of OSI-906 on Ewing sarcoma cells in vitro." (PMID 33260481, 2020). "Moreover, when Ewing sarcoma cells were exposed to exogenous IGF1 and/or insulin, metformin prevented IGF-1 and Insulin-induced proliferation and maintained its anti-proliferative effects." (PMID 24391834, 2013).
fatty acid metabolism disorder (2 papers, 2019 to 2025). "The content of inositol in the model group was significantly increased, suggesting that high-fat diet feeding may cause insulin signal transduction dysfunction and fatty acid metabolism disorder in rats." (PMID 30881991, 2019).